GSK3B (glycogen synthase kinase 3 beta)
Diseases named in the same sentence as GSK3B in open-access papers (continued):
Sharing a sentence is not in itself a finding about the gene and the disease.
prostate carcinoma (continued). "In this study, the importance of GSK-3β activity for the maintenance of prostate cancer stem/progenitor-like subpopulation and its involvement in metastasis was evaluated." (PMID 25344861, 2014). "The striking anti-tumor effects of GSK-3β inhibition in vitro were paralleled by a significant decrease in subcutaneous growth and bone metastasis in vivo of the osteotropic prostate cancer cell line PC-3M-Pro4." (PMID 25344861, 2014). "It has been reported that mostly GSK-3β expression is up-regulated in many types of cancer, including prostate cancer." (PMID 24519956, 2014). "We evaluated the effect of GSK-3β inhibition on the prostate cancer stem/progenitor-like subpopulation, and subsequently on functional cellular characteristics such as the clonogenic and migratory capacity." (PMID 25344861, 2014). "To this end, we identified Glycogen Synthase Kinase-3β (GSK-3β) as a crucial kinase for the maintenance of prostate cancer stem/progenitor-like cells and pharmacologic inhibition of GSK-3β dramatically decreased the size of this cellular subpopulation." (PMID 25344861, 2014). "We also demonstrate that GSK-3β activation by Src-mediated Y216 phosphorylation augments prostate cancer cell function in vitro and tumor xenograft growth in vivo." (PMID 24519956, 2014). "For example, GSK3β was shown to inhibit growth of prostate cancer cells thus acting as a tumor suppressor." (PMID 25937997, 2014). "Compared to normal prostate, GSK-3α and GSK-3β were up-regulated in prostate cancer with GSK-3α elevated in low Gleason tumors and GSK-3β expressed in high Gleason tumors." (PMID 24519956, 2014). "Our study also unveils the potential benefits of dasatinib in the management of prostate cancer by inhibiting Src- GSK-3β pathway, although further pre-clinical and clinical validation is desirable." (PMID 24519956, 2014). "The strong effects observed in multiple prostate cancer cell lines suggest cell-type independency of GSK-3β inhibition." (PMID 25344861, 2014). "As expected, inhibition of GSK-3β resulted in increased Wnt signaling in the tested prostate cancer cell lines." (PMID 25344861, 2014). "Next, GSK-3β inhibition strongly attenuated the clonogenic capacity of tested prostate cancer cell lines PC-3 (68% inhibition), PC-3M-Pro4 (-97%), C4-2B4 (-94%) and DU-145 (-44%)." (PMID 25344861, 2014). "Of particular interest is that DAB2IP differentially regulates GSK3β activity in hMSCs and prostate cancer cells; DAB2IP activates GSK3β in prostate cancer cells but represses GSK3β in hMSCs." (PMID 24073285, 2013). "Genistein treatment of prostate cancer cells upregulates the expression of GSK3β, enhances GSK3β binding to β-catenin, and increases β-catenin phosphorylation, resulting in inactivation of Wnt/β-catenin and inhibiting cancer growth." (PMID 24188694, 2013). "For example, GSK-3β has been shown to inhibit androgen receptor-stimulated cell growth in prostate cancer, thus acting as a tumor suppressor." (PMID 22675363, 2012). "In human prostate cancer cell lines transfected with the fat-1 gene, proliferation was inhibited through a reduction in GSK-3β phosphorylation and a subsequent downregulation of β-catenin and cyclin D1." (PMID 21655218, 2011). "Considering the well-documented role of GSK3β in cancer progression and resistance to therapy, our findings indicate that IL-24-based treatments might provide a novel approach to targeting prostate cancer cells while reducing effects on normal tissues." (PMID 40072085, 2025). "A Co-IP experiment was performed to detect the relationship between EPHB1 and GSK3B protein, which has been reported to be involved in apoptosis, migration, and invasion in prostate cancer, and the results confirmed the interaction between EPHB1 and GSK3B protein." (PMID 40548257, 2025). "HE4 suppresses prostate cancer metastasis by inactivating EGFR/AKT/GSK3B/Snail signaling pathway." (PMID 38304432, 2024).
prostate carcinoma (continued). "GSK3β was effective in β-catenin degradation in prostate cancer (PC)." (PMID 39187523, 2024). "The Akt pathway contributes to prostate cancer development and progression through interacting with other cell signaling pathways important for cellular survival, proliferation, and differentiation, including the GSK-3β/β-catenin signaling pathway." (PMID 37047425, 2023). "Moreover, in human prostate cancer cells, lithium inhibited GSK3β, inducing cell death by modulating Bif-1, and in parallel induced an extensive autophagic response." (PMID 36836894, 2023). "They subsequently demonstrated in both PC-3 and LNCaP prostate cancer cell lines that melatonin administration significantly inhibited hypoxia-mediated phosphorylation of Akt and GSK-3β, which they determined was secondary to melatonin-induced inhibition of SPHK-1." (PMID 37191417, 2023). "Additionally, ABHD2 is targeted by antibody molecules, and GSK3B is targeted by lithium carbonate inhibitor which has currently completed phase 1 trial in prostate cancer." (PMID 36468011, 2022). "Interestingly, in 5/9 genes (55.5%), i.e., ABHD2, DICER1, GSK3B, NR3C1, and NFIB mutations were localized to functional domains of their corresponding proteins, which suggest them to be highly critical genes for prostate cancers." (PMID 36468011, 2022). "Furthermore, it was shown to participate in an inhibition of Akt and GSK-3β activation in prostate cancer cells." (PMID 36432013, 2022). "In addition, a miR-425-5p mimic suppresses the expression of cyclin D1 and targets GSK3β, to increase the sensitivity of prostate cancer cells to cisplatin." (PMID 33406670, 2021). "Previous studies showed that GSK-3β and NF-κB have important roles in prostate cancer." (PMID 32365809, 2020). "GSK-3β expression and NF-κB activities have important roles in prostate cancer development." (PMID 32365809, 2020). "Similarly, inhibition of GSK3-β represses cell viability in models of glioblastoma, leukaemia, ovarian, breast or prostate cancers." (PMID 31362447, 2019). "Moreover, some studies demonstrated that Src-mediated Y216 GSK-3β phosphorylation and activation increased prostate cancer cell motility, proliferation, micrometastasis, and progression." (PMID 31888532, 2019). "This suggested that GSK-3β activity can be modulated by Src kinases and that the pharmacological inhibition of Src-GSK-3β pathway may be a useful therapeutic strategy for prostate cancer." (PMID 31888532, 2019). "However, a putative CRM1 binding site was identified near the C-terminus of the AR, and the rapid nuclear export of AR that occurs upon inhibition of GSK-3β in prostate cancer cells is blocked by Leptomycin B29,30." (PMID 30644418, 2019). "When analyzing pathways associated with colorectal and prostate cancers, we observed that miRNAs targeting both NMT1/2 and MetAP2 genes also regulate the expression of key genes involved in these pathways, including AKT1, GSK3B, BRAF, MAPK and many others." (PMID 29579063, 2018). "In AKT/GSK-3β signalling pathway, AKT could inhibit GSK-3β activity and promote Snail protein stability and participate in metastasis of prostate cancer." (PMID 29262637, 2017). "miR-493-5p inhibits EMT via AKT/GSK-3β/Snail signaling in prostate cancer." (PMID 29137265, 2017). "Furthermore, NQO2 was reported to regulate the stability of cyclin D1 in CWR22Rv1 prostate cancer cells by AKT/GSK‐3β signal pathway." (PMID 27165481, 2016). "In addition to Akt, its downstream signaling pathways such as GSK-3β inactivation and NF-κB activation were also involved in Akt-mediated Snail expression in prostate cancer cells as well as in other cancer types." (PMID 27455254, 2016). "Furthermore, GSK3β is a kinase involved in prostate cancer stemness and migration through a Wnt-independent mechanism." (PMID 26895471, 2016).
prostate carcinoma (continued). "However, the observed functional overlap between GSK3α and GSK3β gene silencing on cell motility, invasion and micrometastasis in vivo questioned if prostate cancer metastasis is a redundant function of both the GSK3 isoforms." (PMID 25714023, 2015). "In contrast, the promotion of epithelial to mesenchymal transition (EMT) and acquisition of invasive and metastatic property in advanced prostate cancer cells is more dependent on GSK3β-mediated inhibition of β-catenin expression and destabilization of cell-cell contacts." (PMID 25714023, 2015). "Hence, we next determined the effect of isoform specific knockdown of GSK3α and GSK3β in prostate cancer cells on their motility and transendothelial migration (microinvasion)." (PMID 25714023, 2015). "In HCC specifically, the suppression of NDRG1 expression and function, including disruption of its interactions with GSK-3β and Nur77, are all potential means of therapeutic interventions, although in prostate cancer, the reverse may be beneficial." (PMID 26359353, 2015). "Also, inhibition of GSK-3β activity resulted in a strong decrease in cellular migration of all tested prostate cancer cell lines; PC-3 (92% inhibition), PC-3M-Pro4luc2 (-88%), C4-2B4 (-87%) and DU-145 (-71%)." (PMID 25344861, 2014). "Taken together, our mechanistic observations highlight the importance of GSK-3β activity in prostate cancer stemness and may facilitate the development of novel therapy for advanced prostate cancer." (PMID 25344861, 2014). "Current findings with pharmacologic GSK-3β inhibitors may, thus, facilitate the development of novel therapy for incurable, advanced prostate cancer." (PMID 25344861, 2014). "Hence, it appears that GSK-3β activity is involved in prostate cancer stemness and migration via a Wnt-independent mechanism." (PMID 25344861, 2014). "In addition, other studies show anti-tumor effects of GSK-3β inhibition on prostate cancer cells in vitro, but these effects were predominantly attributed to modulating effects on the androgen-receptor axis, or changes in cell cycle proteins." (PMID 25344861, 2014). "Additionally, GSK-3β expression and NFκB activity have important roles in prostate cancer development." (PMID 23213321, 2012). "The recent finding that inhibition of the glycogen-synthase-kinase 3β (GSK-3β) induces a rapid nuclear export of the AR in androgen-stimulated prostate cancer cells prompted us to analyze the effects of a GSK-3β inhibition in the castration-resistant LNCaP sublines C4-2 and LNCaP-SSR." (PMID 21980429, 2011). "Intracellular levels of AR, PSA and GSK-3β in different prostate cancer cell lines." (PMID 21980429, 2011). "One study insisted, AMPK/GSK3β/β-catenin cascade triggered KIAA1199 over-expression may promote migration and invasion in anoikis-resistant prostate cancer cells by increasing PDK4-associated metabolic reprograming, which may provide a novel therapeutic target for the prostate cancer." (PMID 33194340, 2020). "Moreover, a recent in vitro and in vivo study showed that targeting Src-mediated GSK3β phosphorylation at Tyr216 could inhibit prostate cancer progression." (PMID 29747452, 2018). "This further supports the hypothesis that the increased PP2A stability caused by low levels of miR-16 and miR-124 in a subset of androgen independent prostate cancer cell lines could explain reduced cell migration and invasion, an effect that we also documented upon GSK3β inhibition." (PMID 25883651, 2015). "Notably, 100 μM PNU-74654 significantly reduced migratory potential under basal and GSK-3β inhibitory conditions, suggesting that active Wnt signaling may, in fact, be positively correlated with migration of prostate cancer cells." (PMID 25344861, 2014). "Therefore, we examined whether the Akt-GSK-3β-Cyclin D1 pathway was involved in BP-induced degradation of cyclin D1 in prostate cancer cells." (PMID 22470469, 2012).
prostate carcinoma (continued). "We showed for the first time that IL-24 inhibits GSK3β and involves phosphorylation at serine 9 by protein kinase A (PKA) and threonine 390 by p38 MAPK in prostate cancer cells." (PMID 40072085, 2025). "Our analysis revealed that several maize miRNAs potentially target key regulators of prostate-cancer signaling, including PTEN, IGF1R, AR, FOXO1, GSK3B, and BCL2." (PMID 41440174, 2025). "Our findings demonstrate for the first time that IL-24 exerts its pro-apoptotic effects in human prostate cancer cells by activating the PKA pathway and subsequently inhibiting GSK3β." (PMID 40072085, 2025). "In prostate cancer, HJURP increased the ubiquitination of cyclin-dependent kinase inhibitor one via the GSK3β/JNK signaling pathway, decreasing its stability and thereby promoting cell proliferation." (PMID 39649097, 2024). "For example, in prostate cancer cells, inhibition of PI3K by Apigenin has been shown to prevent activation of phosphorylation of glycogen synthase kinase-3 beta (GSK-3β), a target of Akt." (PMID 38791608, 2024). "The CXCR6‐CXCL16 axis also promotes docetaxel resistance through phosphorylation of GSK‐3β, NF‐κB and ERK1/2, as well as angiogenesis in prostate cancer via AKT/mTOR‐mediated regulation of VEGF and IL‐8." (PMID 36608258, 2023). "They concluded that mechanistically, melatonin inhibits HIF-1α stabilization and nuclear translocation in prostate cancer cells via inactivation of the SPHK-1 and Akt/GSK-3β, culminating in the demonstrated anti-angiogenic activity." (PMID 37191417, 2023). "In summary, in prostate cancer cells, TUBB4A facilitates tumor growth and metastasis through MYH9-mediated GSK3β/β-catenin signaling." (PMID 35589707, 2022). "In comparison, there were no obvious associations between the expression levels of ABHD2, FGF2, DCAF7, GSK3B, NACC2, DICER1, and FGFR1OP genes and survival rate in prostate cancer patients." (PMID 36468011, 2022). "Of the 32 target hub genes, 4 were mapped to cell signalling pathways including ACVR1 and ACVR2B in TGF-beta signalling, CDKN1A and GSK3B in ErbB signalling (adj.P val = 0.016) and CDKN1A and GSK3B genes in Prostate cancer pathways (adj." (PMID 36468011, 2022). "In prostate cancer and glioblastoma multiforme, DAB2IP induced β‐catenin degradation by inhibiting GSK‐3β phosphorylation at S9." (PMID 36536485, 2022). "In the present study of prostate cancer cells, TUBB4A directly interacted with MYH9 and reduced GSK3β ubiquitination and degradation." (PMID 35589707, 2022). "Our bioinformatics analysis from TCGA dataset showed, for prostate cancer tissues, a positive correlation of mRNA expression of MYH9 with mRNA expression of GSK3β, β-catenin, cyclin D1, c-MYC, vimentin, and N-cadherin." (PMID 35589707, 2022). "ST6GAL1 silencing attenuated proliferation and colony formation ability of PC-3 and DU145 prostate cancer cell lines, through inhibition of the PI3K/AKT/GSK-3β/β-catenin pathway." (PMID 33921986, 2021). "Consistently, GSK-3β inhibitors such as lithium chloride enhance TRAIL-mediated apoptosis in human gastric adenocarcinoma and human prostate cancer cell lines." (PMID 34832080, 2021). "In prostate cancer cells, ST6GAL1 silencing inhibited cell migration and invasion through downregulation of the PI3K/AKT/GSK-3β/β-catenin pathway." (PMID 33921986, 2021). "Dynamic interactions among GSK3β, AMPK and β-catenin have been found to be important in controlling metabolic reprogramming, migration, and invasion in anoikis-resistant prostate cancer cells." (PMID 34975828, 2021). "In prostate cancer cells, invalidation of TRPM4 increases GSK3β activity, leading to β-catenin degradation." (PMID 33117152, 2020). "In multiple human cell lines, such as bladder cancer and prostate cancer cells, levels of the DNMT1 and DNMT3β proteins are modulated by the PI3K/AKT/glycogen synthase kinase 3β (GSK3β) signaling pathway." (PMID 29467020, 2018).
prostate carcinoma (continued). "AZD5363 inhibits phosphorylation of AKT substrates GSK3β and PRAS40 and the downstream biomarker S6 in cell lines, including LNCaP prostate cancer cells and rodent xenografts including from PC3 prostate cancer cells." (PMID 28144789, 2017). "Kinase inactivation of GSK-3β, such as by the GSK-3β inhibitor AR79, promotes prostate cancer growth and mammary tumorigenesis by activating the canonical Wnt pathway." (PMID 26992223, 2016). "In autochthonous transgenic prostate cancer TRAMP mice, inhibition of GSK3β resulted in reduction of tumor number and size through the derepression of C/EBPα and inhibition of E2F expression." (PMID 26560046, 2015). "Previous studies found EP2/Gαs coupled with PGE2 exerted proneoplastic effects by stimulating critical oncogenic pathways, such as the GSK3β/β-catenin pathway and cAMP/PKA pathway in colon, lung and prostate cancer." (PMID 25781635, 2015). "Recently, Sakamoto and colleagues found that overexpression of Talin-1 enhanced prostate cancer cell adhesion, migration and invasion by stimulating FAK, Src and GSK3β independently of integrin signaling and also conferred resistance to anoikis." (PMID 25925041, 2015). "Glycogen synthase kinase 3 (GSK-3), a serine-threonine kinase is one of the least characterized substrate of Akt in prostate cancer cells, whose activity is inhibited by Akt via phosphorylation at serine 9 and 21 in GSK-3α and GSK-3β isoforms, respectively." (PMID 24519956, 2014). "Based on the strong effects of GSK-3β inhibition on the stem/progenitor cell subpopulation in vitro, we evaluated the effects of GIN pretreatment on prostate cancer tumorigenicity and metastatic potential in vivo." (PMID 25344861, 2014). "Src inhibitor treatment inhibits proliferation of prostate cancer cells through β-catenin, ERK1/2, GSK3β-mediated cyclin D1, and c-Myc regulation." (PMID 24349321, 2013). "A constitutively high concentrations of nuclear beta-catenin was reported in PTEN-null prostate cancer cell lines, and a re-expression of PTEN in those cells resulted in activation of GSK-3β and degradation of beta-catenin." (PMID 24143235, 2013). "Given that STK38 has previously been reported to inhibit β-catenin activity in prostate cancer, we hypothesized that STK38 might modulate GSK3β substrate preference in pRCC." (PMID 41540036, 2026). "Collectively, these findings support GSK3β as a promising therapeutic target in prostate cancer, independent of its role in β-catenin degradation." (PMID 40072085, 2025). "Notably, the selective GSK3β inhibitor GIN reduced clonogenic potential, migration, and the stem-like cell population in various prostate cancer cell lines." (PMID 40072085, 2025). "PC3-LN4 prostate cancer cells lacking PIM1, which display higher GSK3β activation, show a significant decrease in genes linked to peroxisomal biogenesis (peroxisomal biogenesis factor 3 and 5; PEX3 and PEX5) and LD growth (Tip47)." (PMID 38097734, 2024). "It has also been shown that luteolin suppresses Wnt signaling irrespective of GSK-3β in prostate cancer cells by attenuating β-catenin transcriptional activity in GSK-3β-depleted cells." (PMID 37432240, 2023). "The other genes showing molecular alterations in prostate cancer samples from highest to lowest are as follows; FGF2 (94/4990; 1.9%), NFIB (86/4990; 1.7%), CEP43 (62/4990; 1.2%), GSK3B (99/8961; 1.1%), DICER1 (101/8961; 1.1%), NR3C1 (53/4990; 1.1%) and ABHD2 (28/4,990; 0.6%)." (PMID 36468011, 2022). "Interestingly, treatment of prostate cancer cells with troglitazone and either a GSK-3β inhibitor (AR-A014418) or GSK-3β siRNA potentiated the effects of troglitazone on suppression of NF-κB activity." (PMID 32365809, 2020).